LECT2 (leukocyte cell derived chemotaxin 2)
Diseases named in the same sentence as LECT2 in open-access papers (continued):
Sharing a sentence is not in itself a finding about the gene and the disease.
biliary atresia (3 papers, 2021 to 2024). A rare, biliary tract disease characterized by progressive obliterative cholangiopathy of the intra- and extrahepatic bile ducts, occurring in the embryonic/ perinatal period, leading to severe and persistent neonatal jaundice and acholic stool. "LECT2 protein expression in biliary atresia (87.8%) was significantly higher than in control group (7.5%, p < 0.01)." (PMID 34899846, 2021). "Then, we examined the expression of LECT2 in biliary atresia liver tissues and normal liver by qRT-PCR." (PMID 34899846, 2021). "GSE46960 was used to validated the mRNA expression level of LECT2 in biliary atresia." (PMID 34899846, 2021). "LECT2 was highly expressed in the cytoplasm of biliary atresia hepatocytes." (PMID 34899846, 2021). "The mRNA expression of LECT2 was found increased in biliary atresia liver tissues." (PMID 34899846, 2021). "Comparison of LECT2 protein expression between biliary atresia liver tissue and control tissue." (PMID 34899846, 2021).
Cirrhosis (3 papers, 2014 to 2024). A chronic disorder of the liver in which liver tissue becomes scarred and is partially replaced by regenerative nodules and fibrotic tissue resulting in loss of liver function. "Despite a lower LECT2 expression in HCC samples, a relatively higher level of serum LECT2 was observed in HCC patients than in patients with cirrhosis or healthy volunteers." (PMID 35656863, 2022). "Intriguingly, Tukey-Kramer analysis revealed a significant difference in serum LECT2 levels in HCC patients when compared to chronic liver disease patients with cirrhosis (p = 0.0017) and healthy volunteers (p = 0.0078)." (PMID 24892551, 2014). "However, Sak et al19 observed that the level of LECT2 in patients with alcohol‐induced liver cirrhosis decreased with the progression of cirrhosis." (PMID 35656863, 2022). "On the other hand, patients who did not harbor CTNNB1 mutations showed significantly higher LECT2 level (54.26±22.25 ng/mL; n = 46) than those with cirrhosis and from healthy volunteers (p = 0.0044 and 0.0176, respectively)." (PMID 24892551, 2014). "Based on Tukey-Kramer post hoc test, serum LECT2 levels in patients with mutated β-Catenin (54.28±22.32 ng/mL; n = 8) were not statistically different from either patients with cirrhosis (32.8±21.1 ng/mL, p = 0.091; n = 15) or healthy volunteers (33.2±7.2 ng/mL, p = 0.137; n = 11)." (PMID 24892551, 2014). "Interestingly though, irrespective of molecular aberrations, LECT2 levels were significantly higher in all HCC patients versus patients with cirrhosis or healthy controls." (PMID 24892551, 2014).
Renal amyloidosis (3 papers, 2015 to 2024). A form of amyloidosis that affects the kidney. "Moreover, abnormal LECT2 deposition in the liver or kidney is associated with the hepatic or renal amyloidosis, respectively." (PMID 36055405, 2022).
rheumatoid arthritis (3 papers, 2022 to 2024). A chronic, systemic autoimmune disorder characterized by inflammation in the synovial membranes and articular surfaces. "Therefore, it may be reasonable to assume that LECT2 involves in the pathogenesis of human inflammatory disorders, and it may be a useful target for these diseases, such as autoimmune hepatitis and rheumatoid arthritis." (PMID 35656863, 2022).
viral infection (3 papers, 2019 to 2022). "To examine the functional relevance of LECT2 in viral infection, we evaluated LECT2, MET and HGF mRNA expression in the liver of patients with chronic hepatitis C (CHC)." (PMID 35676290, 2022). "Interestingly, we also detected high expression levels of antibacterial genes (SAA, CHTA−2B, CMPK2, CD209, LECT2, and NK−lysin) by RNA−seq, suggesting that viral infection disrupts the microbial balance of the gut." (PMID 36016461, 2022). "LECT2 may serve as a potential therapeutic target not only for viral infection but also for cancer." (PMID 35676290, 2022).
acute myocardial infarction (2 papers, 2023 to 2025). Necrosis of the myocardium, as a result of interruption of the blood supply to the area. "Notably, in patients experiencing acute myocardial infarction, those with elevated LECT2 levels faced a higher likelihood of major adverse cardiovascular events over a 12-month period compared to those with lower levels." (PMID 40284206, 2025).
atopic dermatitis (2 papers, 2023 to 2024). "Previously, we reported that serum LECT2 levels correlate with disease severity in atopic dermatitis (AD) patients." (PMID 39206203, 2024).
coronary artery disease (2 papers, 2017 to 2025). "Additionally, a recent study has linked LECT2 to cardiovascular disease, showing that patients with coronary artery disease exhibit increased LECT2 levels." (PMID 40284206, 2025).
lung carcinoma (2 papers, 2020 to 2021). "FGFR3, LBP, LECT2, and DYNC1I1 were distinguishable markers in lung cancer." (PMID 32528533, 2020).
melanoma (2 papers, 2016 to 2023). A malignant, usually aggressive tumor composed of atypical, neoplastic melanocytes. "In addition to tumor angiogenesis in HCC, we also found that LECT2 reduced MVD and tumor growth in ectopic expression of LECT2 in B16F1 mouse melanoma model (data not shown), suggesting LECT2 broadly suppressed tumorigenesis via tumor angiogenesis." (PMID 27507763, 2016).
metastatic disease (2 papers, 2020 to 2021). "The LECT2 expression was measured in paired primary tumors and metastatic tumors (Lymph node metastasis), respectively." (PMID 33937262, 2021). "LECT2 expression significantly decreased in PDACs, especially the metastatic tumors, indicating the potential suppressive role of LECT2 in this malignancy." (PMID 33937262, 2021). "LECT2, a chemokine-like chemotactic factor, plays a protective anti-inflammatory role in the liver with β-catenin-induced tumorigenesis, and downregulated LECT2 expression results in the presence of inflammatory infiltrates, tumor progression and metastatic disease." (PMID 32514252, 2020).
non-small cell lung carcinoma (2 papers, 2021 to 2024). A group of at least three distinct histological types of lung cancer, including non-small cell squamous cell carcinoma, adenocarcinoma, and large cell carcinoma. "Also, we have recently characterized a suppressive role of LECT2 in non-small cell lung cancer (NSCLC) progression via antagonizing c-Met and epidermal growth factor receptor (EGFR)." (PMID 38177412, 2024).
osteoarthritis (2 papers, 2018 to 2024). A noninflammatory degenerative joint disease occurring chiefly in older persons, characterized by degeneration of the articular cartilage, hypertrophy of bone at the margins and changes in the synovial membrane. "Research on RA, osteoarthritis, and osteoporosis suggests that LECT2 plays a role in controlling bone immune responses, making it crucial for bone health." (PMID 38881894, 2024).
osteoporosis (2 papers, 2023 to 2024). A condition of reduced bone mass, with decreased cortical thickness and a decrease in the number and size of the trabeculae of cancellous bone (but normal chemical composition), resulting in increased fracture incidence. "LECT2 is also found to play a role in the upregulation in serum of osteoporosis patients, is positively correlated with their bone loss, and is a potential biomarker for osteoporosis diagnosis." (PMID 36969200, 2023). "The development of osteoporosis could also be linked to LECT2." (PMID 38881894, 2024). "Recent research indicated that there was a notable increase in serum LECT2 levels in individuals with osteoporosis, which impacted the severity of osteopenia." (PMID 38881894, 2024). "All these results suggest that LECT2 is a potential diagnosis and therapeutic target for osteoporosis." (PMID 36969200, 2023).
overnutrition (2 papers, 2020 to 2021). An imbalanced nutritional status resulting from excessive intake of nutrients. "The overnutrition-induced elevation of LECT2 activates the LPS-induced TAB2-MKK4-JNK axis as an adjuvant, shifts liver residual macrophages to the M1-like phenotype, and contributes to the development of liver inflammation." (PMID 33436955, 2021). "The quantification of LECT2 to elucidate its protein kinetics is a key factor for its development as a clinical biomarker of overnutrition conditions." (PMID 32764719, 2020). "In conclusion, the present study identified that LECT2 has a very short half-life of approximately 5 min in the bloodstream in mice, indicating that LECT2 is a rapid-turnover protein with potential utility in assessing the overnutrition state." (PMID 32764719, 2020). "Based on these findings, we hypothesized that LECT2 links overnutrition to the development of liver inflammation and the subsequent development of NASH." (PMID 33436955, 2021). "Considering the rapid response of circulating LECT2 linked to subsequent body weight alterations, the measurement of serum LECT2 levels might be a clinically useful indicator of overnutrition." (PMID 32764719, 2020).
pancreas cancers (2 papers, 2021 to 2024). "C-Met is overexpressed in lung, breast, ovary, colon, and pancreas cancers, among others, suggesting the LECT2/c-Met regulatory axis may be a common pathway in human cancers." (PMID 38177412, 2024).
sarcopenia (2 papers, 2025 to 2026). Progressive decline in muscle mass due to aging which results in decreased functional capacity of muscles. "Although NAFLD and sarcopenia are closely linked, the relationship between plasma LECT2 levels and sarcopenia remains unclear." (PMID 40284206, 2025). "Further research is needed to elucidate the physiological role of circulating LECT2 in individuals with sarcopenia and explore the generalizability of our findings in different ethnicities." (PMID 40284206, 2025). "Despite these associations, no prior research in humans has specifically investigated the link between circulating LECT2 levels and sarcopenia." (PMID 40284206, 2025). "Future research should incorporate mediation analyses to elucidate the potential mechanistic pathway linking NAFLD, LECT2, and sarcopenia." (PMID 40284206, 2025). "In conclusion, high plasma LECT2 levels are independently associated with an LMM, LMS, and sarcopenia in older Korean adults." (PMID 40284206, 2025). "Additionally, we aimed to examine the risk of an LMM, LMS, and sarcopenia (defined as the presence of both an LMM and LMS) based on the plasma LECT2 levels." (PMID 40284206, 2025). "Given the upregulation of LECT2 levels in NAFLD, these results indicate that LECT2 is a key factor contributing to sarcopenia in patients with NAFLD." (PMID 40284206, 2025). "The participants with an LMM, LMS, and sarcopenia had higher plasma LECT2 levels than those without these conditions." (PMID 40284206, 2025). "Collectively, these findings suggest that LECT2 may serve as a potential mediator linking NAFLD and sarcopenia." (PMID 40284206, 2025). "Additionally, the plasma LECT2 levels were elevated in the individuals with sarcopenia compared to those without the condition (34.8 [29.5–40.6] vs. 31.3 [25.8–37.9] pg/mL, p = 0.031)." (PMID 40284206, 2025). "Compared to the stable nonsarcopenic group, individuals who developed sarcopenia demonstrated significant APOA1 (fold change -1.42, p < 0.001) and KLKB1 downregulation and LECT2 upregulation." (PMID 41782349, 2026). "Despite the fact that LECT2 can be a link between NAFLD and sarcopenia, no human studies have explored the relationship between circulating LECT2 levels and an LMM or LMS." (PMID 40284206, 2025). "Furthermore, the plasma LECT2 levels were elevated in the participants with an LMM, LMS, or sarcopenia compared to their counterparts without these conditions." (PMID 40284206, 2025).
T-cell leukemia (2 papers, 2017 to 2022). A malignant disease of the T-lymphocytes in the bone marrow, thymus, and/or blood. "Leukocyte cell-derived chemotaxin 2 (LECT2) is a multifunctional cytokine, which is initially purified from plant hemagglutinin-activated human T-cell leukemia SKW-3 cell culture." (PMID 35928681, 2022). "Leukocyte cell-derived chemotaxin 2 (LECT2) is a 16-kDa secretory protein that was first isolated in 1996 from cultured supernatants of phytohemagglutinin-activated human T-cell leukemia SKW-3 cells." (PMID 28376109, 2017).
adenoma (1 paper, 2018). A neoplasm arising from the epithelium. "Loss of Lect2 resulted in a significant decrease in survival in our ApcMin/+ mouse model, which was associated with a significant increase in adenoma number in the small intestine." (PMID 30559928, 2018). "The decrease in survival of ApcMin/+Lect2−/− mice correlated with a significantly increased number of adenomas in the small intestine compared to the ApcMin/+Lect2+/+ mice at death (mean of 26.8 tumours versus 15.2 tumours, Mann–Whitney U-test, P = 0.0138)." (PMID 30559928, 2018).
AL amyloidosis (1 paper, 2025). AL Amyloidosis is a plasma cell disorder characterized by the aggregation and deposition of insoluble amyloid fibrils derived from misfolding of monoclonal immunoglobulin light chains usually produced by a plasma cell tumor. "Immunoelectron microscopy did not detect leukocyte chemotactic factor 2 (LECT2) protein, and κ(+) and λ(±) light chains were identified, which closely resemble AL amyloidosis." (PMID 40443630, 2025). "In our case, immunoelectron microscopy revealed κ (+) and λ (±) staining without the detection of LECT2 protein, closely resembling AL amyloidosis." (PMID 40443630, 2025).
Atherosclerotic lesion (1 paper, 2019). A lesion associated with atherosclerosis, a multifactorial and multipart progressive disease manifested by the focal development within the arterial wall of lesions, that ranges from the development of a fatty streak, plaque progression, and plaque disruption. "Results showed that LECT2 reduced total cholesterol and low-density lipoprotein concentrations in serum and inhibited the development of atherosclerotic lesions, accompanied by reductions in inflammatory cytokines and lower MCP-1, MMP-1, TNF-α, IL-8, and IL-1β mRNA abundance." (PMID 31310065, 2019).
breast carcinoma (1 paper, 2020). "For example, EPB41, PSMA1, LEP, LECT2, and ZNF35 were associated with breast cancer." (PMID 32528533, 2020).
cholestasis (1 paper, 2022). Impairment of the bile flow caused by obstruction within the liver, or outside the liver in the bile duct system. "Therefore, LECT2 was able to distinguish BA from other cholestasis with an AUC of 0.95 (95% CI: 0.90–1.00), and the cutoff value was 23.99 ng/ml with a sensitivity of 86% and specificity of 94%." (PMID 35928681, 2022).
colon adenocarcinoma (1 paper, 2022). "For example, LECT2 is considered one of the potential prognostic risk biomarkers for colon adenocarcinoma." (PMID 36160006, 2022).
colorectal cancer (1 paper, 2018). A primary or metastatic malignant neoplasm that affects the colon or rectum. "In summary, in the murine intestine loss of Lect2 promotes the initiation and progression of Wnt-driven colorectal cancer." (PMID 30559928, 2018).
fibrosis (1 paper, 2022). the formation of excess fibrous connective tissue in an organ or tissue in a reparative or reactive process. "In this study, we also suggested that LECT2 is a novel biomarker for the identification of BA, which is achieved by the sensitivity to fibrosis." (PMID 35928681, 2022).
Granuloma (1 paper, 2010). A compact, organized collection of mature mononuclear phagocytes, which may be but is not necessarily accompanied by accessory features such as necrosis. "The presence of severe granulomas was associated with a profile of up-regulation of innate immunity-related genes such as complement factors C1q and C6, mannose binding protein, lysozyme C, C-type lectin receptor, CD209, Cathepsin D, CD63, LECT-2, CC chemokine and metallothionein." (PMID 20507624, 2010).
insulin-resistant diabetes (1 paper, 2023). "In general, it was found that in both mice and humans, serum levels of LECT2 are increased in the case of insulin-resistant diabetes." (PMID 38137613, 2023).
intestinal tumour (1 paper, 2018). "This trend towards a global reduction cytokine levels indicates that Lect2 plays a role in driving or maintaining the inflammatory response that occurs in the presence of Wnt driven intestinal tumours." (PMID 30559928, 2018). "However, our data indicating the loss of Lect2 had no impact on the phenotype of the Apc+/minMbd2−/− mice suggests that epigenetic silencing of Lect2 doesn't play a key role in intestinal tumour initiation but is more relevant to inflammation and tumour progression." (PMID 30559928, 2018).
LECT2 amyloidosis (1 paper, 2020). "Therefore, the identification of the urinary peptides derived from the full-length LECT2 protein might be clinically important for the development of treatments for LECT2 amyloidosis." (PMID 32764719, 2020).
leukemia (1 paper, 2022). A malignant (clonal) hematologic disorder, involving hematopoietic stem cells and characterized by the presence of primitive or atypical myeloid or lymphoid cells in the bone marrow and the blood. "Leukocyte cell-derived chemotaxin 2 (LECT2) was first identified as a 16-kDa secreted protein from cultured medium of phytohemagglutinin-activated SKW-3 leukemia cells and exhibit chemotaxis for human neutrophils." (PMID 36055405, 2022).
lymph node metastasis (1 paper, 2021). "Moreover, the expression level of LECT2 is negatively correlated with tumor size, lymph node metastasis, and distant metastasis." (PMID 33937262, 2021). "LECT2 expression was also correlated with multiple clinical pathologic features, including TNM staging, tumor size, lymph node metastasis, and distant metastasis." (PMID 33937262, 2021).
ovarian carcinoma (1 paper, 2024). A malignant neoplasm originating from the surface ovarian epithelium. "Here, we have demonstrated reduced serum levels of LECT2 in patients with epithelial ovarian cancer (EOC) and down-regulated circulating Lect2 as the disease progresses in a syngeneic mouse ID8 EOC model." (PMID 38177412, 2024).
pancreatic ductal adenocarcinoma (1 paper, 2024). An infiltrating adenocarcinoma that arises from the epithelial cells of the pancreas. "Indeed, LECT2 was found to suppress tumor metastasis by targeting the HGF/c-Met signaling in pancreatic ductal adenocarcinoma (PDAC)." (PMID 38177412, 2024).
primary aldosteronism (1 paper, 2017). An endocrine disorder characterized by excessive production of aldosterone by the adrenal glands. "The LECT2 gene has been associated with adrenal amyloid and primary aldosteronism, which have no or few symptoms." (PMID 28924246, 2017).